CD4 (CD4 molecule)
Diseases named in the same sentence as CD4 in open-access papers (continued):
Sharing a sentence is not in itself a finding about the gene and the disease.
graft versus host disease (98 papers, 2009 to 2025). An immune system disorder that occurs after allogeneic hematopoietic stem cell transplant and is a reaction of donor immune cells against host tissues. "As expected, the majority of mice injected with R5-modified or mock-modified CD4+ T cells showed xenogeneic graft versus host disease (XGVHD) with clinical features of hair loss and dermatitis, which often appear between 47 and 52 days post-engraftment." (PMID 31186067, 2019). "Interestingly, a few studies have reached the conclusion that high numbers of circulating CD4 + CD25 + FoxP3+ cells are associated with reduced incidence of graft versus host disease (GVHD) after allogeneic stem cell transplantation." (PMID 34640606, 2021). "In the setting of haematopoietic stem cell transplantation, several studies demonstrated that the occurrence and severity of graft versus host disease (GvHD) can be associated with reduced levels of Foxp3+CD4+CD25+ Tregs." (PMID 36875063, 2023). "CD8 T cells and, more recently, CD4 T cells specific for minor antigens have been isolated from humans and rodents and have been shown to play an important role in the rejection of solid organs and corneal transplants as well as causing graft-versus-host disease after bone marrow transplantation." (PMID 21476231, 2010). "In patients who survive, secondary prophylaxis is also recommended for those at risk for recurrence (i.e. still remaining of high dose immunosuppression for active graft-versus-host disease, or low CD4 counts)." (PMID 41019280, 2025). "In this model, NSG mice are engrafted with the memory (CD45RO+) subset of CD4+ T cells, which avoids the severe graft versus host disease that rapidly occurs in mice engrafted with total human CD4+ T cells." (PMID 41509258, 2025). "Serum magnesium levels were measured at defined intervals post-transplant, and outcomes were correlated with CD4+ T cell recovery, time to engraftment, incidence of graft-versus-host disease (GVHD), and survival within 12 months." (PMID 40806047, 2025). "In CD4+ T cells, SDHA loss dampened both oxidative phosphorylation (OXPHOS) and glycolysis, impaired cytokine production, proliferation, and reduced CD4+ T cell–mediated graft-versus-host disease after allogeneic stem cell transplantation (SCT)." (PMID 41392980, 2025). "In line with this, allospecific CD4+ T cells that react against host-derived histocompatibility antigens expressed in corneal epithelial cells and nerves are at the heart of ocular graft-versus-host disease." (PMID 37217914, 2023). "In line with our findings, a previous study showed that LAG3-KO CD4+ T cells secrete significantly more IFN-γ and IL-10 than WT CD4+ T cells in murine graft-versus-host disease." (PMID 37172058, 2023). "Activated human CD4+or CD8+ T cells in mice often leads to severe graft-versus-host disease (GVHD), which markedly limits the observation period and making its wide application difficult." (PMID 37646021, 2023). "miR-17-92 also plays an essential role in the activation, proliferation, survival, and differentiation of CD4+ T cells in graft-versus-host disease (GVHD)." (PMID 34039371, 2021). "Therapeutics targeting VISTA curb the development of graft-versus-host disease and promote the death of naive CD4+ T cells; thus, VISTA can be regarded as a distinctive immunotherapy molecule." (PMID 34220791, 2021). "Moreover, few studies have reached the conclusion that high numbers of circulating CD4 + CD25 + FoxP3+ cells are associated with reduced incidence of graft versus host disease (GVHD) after allogeneic stem cell transplantation." (PMID 34640606, 2021). "A subset of granzyme A–producing CD4+ T cells accumulate in the intestines of mice and mediate the development of graft-versus-host disease after hematopoietic cell transplantation." (PMID 32809971, 2020). "Of note, Tc1 cells were also suboptimal in suppressing CD4-induced acute xenogeneic graft versus host disease (xGVHD) in vivo." (PMID 33193343, 2020).
graft versus host disease (continued). "Upon further assessment, MenSCs increased the survival of xeno-graft versus host disease (GVHD) in mice by limiting the proliferation of CD4+IFN-γ+ or CD8+IFN-γ+ T cells exerting an immunosuppressive function." (PMID 31864423, 2019). "CD101 is expressed on CD4+ and CD8+ T-cells, dendritic cells and monocytes, and appears to alter CD4+/CD25+/FOXP3+ T regulatory cell (Treg) function based on both a murine graft-versus-host disease model, and through IL10 secretion from human dendritic cells." (PMID 29108000, 2017). "On the other hand, rapid development of lethal graft-versus-host disease (GVHD) has been observed after administration of cultured CD4+CD25+ T cells with an equal number of CD4+ T cells or CD25 depleted whole T cells." (PMID 29073905, 2017). "Expression of CD103 marks a subset of peripheral inducible Tregs (about 20–30% of the CD4+FoxP3+ Tregs in the spleen), which inhibit graft-versus-host disease more potently than the CD4+CD25+ Tregs." (PMID 24550919, 2014). "Interferon-gamma regulates idiopathic pneumonia syndrome, a Th17+CD4+ T-cell-mediated graft-versus-host disease." (PMID 23843069, 2013). "CD4+interferon (IFN)-γ+ T cell (Th1) and CD4+interleukin (IL)-4+ T cell (Th2) polarizations are crucial in the pathogenesis of graft-versus-host disease (GVHD)." (PMID 22957070, 2012). "CD8+Foxp3+Tregs have been identified during graft versus host disease (GVHD) reactions and regulate allotransplant-associated immune responses by lowering its severity, but are less potent immunosuppressors than conventional CD25+CD4+Foxp3+Tregs." (PMID 41009359, 2025). "Despite these in vitro findings, however, the absence of Piezo1 prevents autoimmune and alloimmune inflammation in in vivo models of experimental autoimmune encephalomyelitis (EAE), IBD, and graft-vs-host disease (GvHD) with a decrease in the CD4+ T-cell effector memory (TEM) population." (PMID 39492686, 2025). "Furthermore, Ohnuma and colleagues outlined that CD26+ CD4+ T cells constitute a significant source of IL-26 in a mouse model of graft-versus-host disease (GVHD)." (PMID 36294822, 2022). "A low CD4+FOXP3+ T-cell count early after HSCT was associated with an increased risk of aGVHD, and the ratio of Tregs to effector T cells was significantly reduced in patients with graft-versus-host disease." (PMID 35053223, 2022). "Taking these into account, it could be hypothesized that hypomethylating agents-induced CD4+HLA-G+FOXP3-T cells in vitro would be adoptive cellular immunotherapy against acute graft-versus-host disease." (PMID 33709198, 2021). "We had shown earlier that ND human (hu) IgG4 specific for huCD4 (clone CH5g5) and huCD8α (clone CH9d2) induces egress of pathogenic CD4+ and CD8+ T cells from inflamed tissues in NRG.PBL humanized mice, which develop xenogeneic graft-versus-host disease (xGVHD)." (PMID 34314385, 2021). "After allogeneic hematopoietic cell transplantation (allo-HCT), adoptively transferred allogeneic CD4+ T cells from FVB/N (H-2q) mice homed to the transplanted mLNs in C57BL/6 (H-2b) recipients during the initiation phase of acute graft-versus-host disease (aGvHD)." (PMID 34381447, 2021). "Furthermore, the increased expression of CD73 on CD4+ T cells was still detected in the blood of mice 50 days after the induction of graft-versus-host disease (GvHD)." (PMID 31998324, 2019). "While MSC transplantation has been shown to suppress the proliferation of CD4+ T cells in a mouse model of graft-versus-host disease, it was uncertain whether the finding in the current study reflected reduced proliferation, or reduced recruitment of cells." (PMID 28173831, 2017). "CD4+CD25highFOXP3+ regulatory T (Treg) cells, which include thymus-derived and peripherally induced cells, play a central role in immune regulation, and are therefore crucial to prevent graft-versus-host disease (GVHD)." (PMID 26210500, 2015).
graft versus host disease (continued). "However, nTreg mediated suppression is not antigen-specific and requires high ratios, usually >1:1 of nTreg:effector CD4+ T cells to inhibit organ allograft rejection or graft versus host disease (GVHD)." (PMID 24847323, 2014). "Similarly, in autoimmune models such as experimental autoimmune encephalitis (EAE) and graft-versus host disease (GvHD) murine models, a high salt diet induced inflammatory activation and effector CD4+T cell responses to self-antigens, and at the same time decreased immunosuppressive Treg responses." (PMID 33918403, 2021). "However there are also several limitations of the NSG model, including poor CD4+ T cell–dependent responses, long-term problems associated to graft-versus-host disease, hemophagocytic lymphohistocytosis, and lack of immunoglobulin isotype switching." (PMID 31550241, 2019). "Tregs inhibit the donor CD4+ and CD8+ T cells, leading to T cell loss of function and may reduce the expression of the molecule at the antigen presenting cell surface, which is required for T cell activation; thus, reducing graft versus host disease (GVHD)." (PMID 24270972, 2014). "Notably, we observed overall higher percentages of donor B cells and CD4+ T cells in allogeneic graft tissues, which are both involved in Graft versus Host Disease (GvHD) pathogenesis." (PMID 40607410, 2025). "Our data show that mature CD4 T cells from TCF-1 cKO mice did not cause graft versus host disease (GvHD) during allogeneic CD4 T cell transplantation, and donor CD4 T cells did not cause GvHD damage to target organs." (PMID 36901757, 2023). "Type I IFNs were shown to interpose the processes of graft-versus-leukemia (GVL) and graft-versus-host disease (GVHD) by reducing alloreactive donor T-cell expansion, thus providing protection from CD4-dependent GVHD." (PMID 34571733, 2021). "For instance, vasoactive intestinal peptide (VIP) has been demonstrated to generate CD4+CD25+ regulatory T cells in vivo and inhibit graft-versus-host disease in an animal model." (PMID 33176790, 2020). "Instead of KO mice, Maillard and colleagues used the dominant negative form of MAML (DN-MAML)-expressing mice and analyzed its effects on CD4+ and CD8+ T cells in a graft-versus-host disease (GVHD) model." (PMID 29441071, 2018). "Adoptive transfer of CD4+CD25+ T regulatory cells has been shown to prevent graft rejection and graft-versus-host-disease (GVHD) in animal models." (PMID 21476231, 2010). "TGFβ has also been shown to induce CD4+CD25+ regulatory T cells in vitro, which were able to prevent a murine lupus-like syndrome and graft versus host disease." (PMID 19173720, 2009). "Detection of viremia in the NSG mouse viral outgrowth assay (mVOA) model is quite variable and may rely on the initial frequencies of infected CD4+ T cells transplanted, the level of expansion of these cells mediated by mechanisms such as graft versus host disease (GvHD)." (PMID 40473838, 2025). "In vivo evaluation of METTL3 inhibition on CD4+ T-cell activation, effector T-cell differentiation, and SLE pathogenesis was achieved using a sheep red blood cell (SRBC)-immunized mouse model and a chronic graft versus host disease (cGVHD) mouse model." (PMID 37013484, 2023). "Also, patients with severe graft versus host disease after hematopoietic stem cell transplantation, after solid organ transplantation, CMV lung infection, and CD4 count less than 100 cells/mm3 have a higher incidence of IPA." (PMID 27445566, 2016). "Adoptive transfer of ex vivo expanded CD4+CD25+ Tregs prevents pathology in various mouse models including graft versus host disease (GvHD), and GvHD was the first disease to be tried in translation studies in humans." (PMID 32235689, 2020).
graft versus host disease (continued). "In agreement with previous studies, the lack of mouse MHC class I molecules in B2m-NOG mice, due to β2-microglobulin gene deletion (B2m), allowed preferential engraftment of CD4 T cells over CD8 T cells and delayed the onset of xenogeneic graft versus host disease (GVHD)." (PMID 40432752, 2025). "Mimicking graft versus host disease (GvHD) during allogenic hematopoietic transplantation (allo-HCT) in the mouse system showed ameliorated GvHD in donor CD4+ T cells with no functional expression of Nrf2 compared to allo-HCT from Nrf2 wild type mice." (PMID 33348637, 2020). "Unlike CD4+Foxp3+ Tregs, these cells suppressed T cell responses regardless of Foxp3 expression, and they also played a role in the spontaneous liver tolerance and autoimmunosuppression of stimulatory graft-versus-host disease (GVHD) with a lupus-like syndrome." (PMID 31402273, 2019). "The objective of the present study was to identify a BETi which did not interfere in vivo with CD4+FoxP3+ regulatory T cell (Treg) expansion and function so it could be utilized together with Tregs following aHSCT to ameliorate graft-versus-host disease (GVHD)." (PMID 30733722, 2018). "Recent variants of these strains lacking MHC class I molecules (B2m) show increased CD4 to CD8 ratios and a longer time window before onset of xenogeneic graft versus host disease (GVHD) and represent improved strains for the study of human immune responses." (PMID 38900149, 2024).
dengue (96 papers, 2006 to 2025). "Levels of IL-10 and IFN-γ, which have previously been shown to be produced by CD4+ T cells and linked to dengue disease, also appeared correlated with each other." (PMID 39088280, 2024). "The elevated level of IgG2a in a mouse model is considered significant for dengue vaccine efficacy in association with the Th1 subset of CD4+ T cells secreting IFN-γ and TNF." (PMID 38250905, 2024). "Here, we observed that an increased frequency of CD4+CD8+ DP T cells during acute DENV infection was associated with development of plasma leakage in dengue disease." (PMID 35062294, 2022). "We report that a population of CD4+CD8+ double-positive (DP) T cells detectable in the peripheral blood is associated with risk of plasma leakage in dengue disease." (PMID 35062294, 2022). "For example, it was observed that subjects positive for certain HLA-DRB1 alleles had a reduced risk of hospitalisation due to dengue, which correlated with higher-magnitude CD4+ T-cell responses." (PMID 32549226, 2020). "Although not only HLA class I alleles but also HLA class II alleles have been associated with increased susceptibility to the severe forms of dengue, fewer studies had assessed pathogenic effects of CD4+ T cells." (PMID 32549226, 2020). "Using an 8-color flow cytometry panel, we then measured the number of CD3+ CD4+ or CD3+ CD8+ T cells producing cytokines that have been implicated in natural dengue disease: IFNγ, TNFα, IL2, and IL10." (PMID 22816004, 2012). "In this study, we observed increased frequency of a novel CD4+CD8+ double-positive (DP) T-cell subset in the acute febrile phase of the DENV infection is associated with risk of developing plasma leakage later in dengue disease." (PMID 35062294, 2022). "However, when antigens (proteins) encoded by the Dengue polyprotein were tested, for some of the proteins the magnitude of CD4+ T cell response was higher for HLA-DQ or HLA-DP." (PMID 31921155, 2019). "Thus, together these results suggest that during a secondary infection, progression to uncomplicated dengue is associated with the expansion of CD4+ and CD8+ T cells consistent with an effector memory phenotype and expressing high levels of co-stimulatory molecules." (PMID 37055751, 2023). "Thus, increased abundance and functionality of cytotoxic CD4 Temra cells may be associated with enhanced protection against severe dengue disease." (PMID 28003809, 2016). "Recent studies have uncovered the significance of highly polarized CX3CR1+ cytotoxic CD4+ T cells in dengue." (PMID 40431664, 2025). "Our previous studies reported the modulation of CD4+ T cells by EV isolated from the plasma of severe dengue patients." (PMID 39745465, 2025). "The dual role of CD4+ T cells in protection and immunopathogenesis underscores the challenges of dengue vaccine development." (PMID 40431664, 2025). "The dual roles of CD8+ and CD4+ T cells in protection and immunopathogenesis underscore the complexity of dengue immunity." (PMID 40431664, 2025). "In dengue, CD4+ T cells primarily recognize peptides of 12–15 amino acids presented by APCs on MHC class II molecules." (PMID 40431664, 2025). "Our present study highlights the impact of severe dengue patients’ plasma-derived EV (SD-EV) on CD4+ T cells and together induce endothelial barrier dysfunction." (PMID 39745465, 2025). "In dengue, T cells, especially γδ, CD4+, and CD8+ subsets, show increased PD-1 and TIM-3 expression, sometimes linked to impaired function." (PMID 40469309, 2025). "In this context, senescent-like CD4+-CTLs that are cross-reactive to different dengue serotypes have been identified in patients with severe dengue fever." (PMID 39497830, 2024). "Of the experimentally validated globally reported dengue-specific 1305 CD4 and 584 CD8 epitopes compiled, we found 24% and 41%, respectively, were conserved universally, whereas 17% and 13% were absent in any viral isolates from India." (PMID 38793612, 2024).